CDKN2A (cyclin dependent kinase inhibitor 2A)
Diseases named in the same sentence as CDKN2A in open-access papers (continued):
Sharing a sentence is not in itself a finding about the gene and the disease.
infection (continued). "Infection of B cells carrying a knockout of CDKN2A with wildtype and EBNA3 oncoprotein mutant strains of EBV allowed us to conclude that EBNA3C controls CDKN2A, the only barrier to B cell proliferation in EBV infected cells." (PMID 33857265, 2021). "Two days after infection, the CMV promoter directed significantly higher CDKN2A expression compared to the hACTB promoter both in the DLD-1 and the MCF-10A cell lines." (PMID 25170953, 2014). "There was a demonstrable increase in p16INK4a (CDKN2A) expression, reduced telomerase activity, and telomere shortening during the acute infectious phase when pairwise compared to the healthy individual at 12-month post infection." (PMID 39620151, 2024). "The overwhelming majority of changed miRNAs were downregulated after infection and infection plus SP-A2 (1A0) protein rescue, and these were predicted to target genes that play a role in cell cycle and growth and proliferation pathways, such as CCND1, CCND2, CDK7, CDKN2A, E2F1, E2F2, E2F3, and MYC." (PMID 35844510, 2022). "However, transforming hrHPV infection results in a lack of RB, evoking expression of the CDKN2A product P16INK4A." (PMID 35676700, 2022). "However, both persistent and short-term epigenetic events may occur during UPEC in vitro infection, as the EZH2 and CDKN2A DNA methylation data reveals." (PMID 26964089, 2016).
adenocarcinoma (56 papers, 2007 to 2025). A common cancer characterized by the presence of malignant glandular cells. "In such cases, several genetic abnormalities are thought to occur for causing this transition from adenocarcinoma to endocrine carcinoma, one of which is the CDKN2A gene abnormality." (PMID 36044167, 2022). "Finally, we observed a trend toward significant decreases in ARID1A and CDKN2A mutations across CCNE1-amplified EG adenocarcinoma." (PMID 38717153, 2024). "Furthermore, the proportion of tumors with Cdkn2a mutations increased in adenocarcinomas." (PMID 37845228, 2023). "Pancreatic (53.9%) and biliary tract (36.3%) adenocarcinomas were the most common digestive adenocarcinomas with CDKN2A alterations." (PMID 38672586, 2024). "The frequency of CDKN2A alterations in pancreatic (47.8%) and biliary tract (31.1%) adenocarcinomas was significantly higher than that in stomach (17.5%) and colorectal (1.4%) adenocarcinomas (p < 0.01)." (PMID 38672586, 2024). "In an adenocarcinoma that was found to have homozygous deletion of CDKN2A, mTAP expression was lost in a subset of neoplastic cells." (PMID 35565429, 2022). "The other genes that were much more mutated in SCC (with estimated mutation proportion in SCC and in adenocarcinoma, respectively) were LRP1B (23%, 10%), KMT2D (16%, 7%), FAT1 (15%, 5%), CDKN2A (12%, 2%), NOTCH1 (10%, 3%), and NFE2L2 (10% and 1%)." (PMID 34645806, 2021). "P16 (CDKN2A) is a tumor suppressor gene that is hypermethylated at a prevalence of up to 67% in adenocarcinoma and 70% in squamous cell carcinoma of the lung." (PMID 24212941, 2011). "LOH at the CDKN2A locus was observed in 68% of adenocarcinomas and 55% of premalignant lesions." (PMID 40149421, 2025). "While alterations in the Cdkn2a gene are associated with NSCLC, surfactant protein C is a marker of alveolar type II cells, which have been believed to be the original cell source of adenocarcinomas and NSCLC." (PMID 34912233, 2021). "While studies representing a lower rate of these mutations mostly contain adenocarcinoma histological type, the higher numbers of MTAP and CDKN2A/B alteration incidences in our case could be due to squamous NSCLC patients, who accounted for 1/3 of all patients." (PMID 40650126, 2025). "However, a CDKN2A deletion in mutant KRAS-expressing mice prevented the progression to senescence and led to invasive and metastasizing adenocarcinomas with morphological and molecular features similar to KRAS-mutated adenocarcinomas." (PMID 29690599, 2018).
adenocarcinoma (continued). "Previous studies have shown that abnormal methylation patterns of genes (APC, CdH1, CDKN2A, and ESR1) are not only limited to adenocarcinoma tissues but also found in precancerous BE tissues." (PMID 34222478, 2021). "Their results showed two hypomethylated genes (CDKN2A and MGMT) and three hypermethylated genes (CDH13, RUNX3, APC) in adenocarcinomas compared with SCC, with the higher sensitivity and specificity values of CDH13 and APC." (PMID 32604993, 2020). "Several of the identified mGISTIC regions harbored known or putative adenocarcinoma driver candidates, such as EGFR, MDM2, KRAS, MYC, TERT, MET, CCND1, NKX2-1/TITF1, CDK4, ERBB2, ID1, RB1, CDKN2A and PTEN." (PMID 24205279, 2013). "APC, KRAS, and CDKN2A were focused on in the present study, and cases with adenocarcinomas were classified based on the presence or absence of each alteration." (PMID 38672586, 2024). "CDKN2A abnormalities were more often seen in nonadenocarcinoma than adenocarcinoma, but the difference was not statistically significant (40.9% versus 27.5%) (P > 0.05)." (PMID 22619677, 2012).
CNS tumors (30 papers, 2009 to 2026). "Molecular features such as IDH mutations and CDKN2A/B deletions have become central to diagnosis and prognostication in the 2021 WHO classification of CNS tumors." (PMID 42294286, 2026). "With these findings, we can conclude that MTAP IHC is a reliable surrogate biomarker that shows high sensitivity and specificity for detecting CDKN2A HD in diffuse gliomas as well as other CNS tumors." (PMID 38109891, 2024). "However, no comprehensive studies have shown the pathophysiological mechanism of CDKN2A deletion in the poor outcomes of CNS tumors." (PMID 39457569, 2024). "In summary, our findings demonstrate that RIGs are an aggressive, relatively homogenous group of CNS tumors with recurrent amplification of PDGFRA and loss of CDKN2A/B in the absence of somatic H3/IDH hotspot mutations." (PMID 34545083, 2021).
cardiovascular disease (24 papers, 2012 to 2025). "As a cardiovascular disease hotspot, p16INK4a and p14ARF are encoded by CDKN2a near the 9p21.3 genomic region." (PMID 36852326, 2023). "Very little is known about this but CDKN2A polymorphisms are associated with both increased cardiovascular disease (CVD) and T2D36." (PMID 31227697, 2019). "Studies have associated single nucleotide polymorphisms on chromosome 9p21 close to the cyclin-dependent kinase inhibitor 2A/B (CDKN2A/B) with risk for cardiovascular disease (CVD) in the general population." (PMID 28192277, 2017). "The arterial expression of CDKN2A/p16INK4a was significantly higher in patients with coronary calcification (p=0.01) and associated cardiovascular disease (CVD) (p=0.004)." (PMID 28192277, 2017). "In the mouse heart, the pool of p16/Cdkn2a+ senescent cells also increases with age and their clearance reverts age‐related phenotypes in cardiovascular disorders and improves heart function in chronologically aged mice." (PMID 34092006, 2021). "The genomic region at 9p21 chromosome near the CDKN2A/CDKN2B genes is associated with type 2 diabetes(T2D) and cardiovascular disease(CVD)." (PMID 23134948, 2012). "For example, Antisense Noncoding RNA in the INK4 Locus (ANRIL), which resides in the cardiovascular disease susceptibility locus 9p21, encodes a lncRNA that regulates Cyclin-Dependent Kinase Inhibitor (CDKN)2A and B expression or circularizes to mediate atherogenic functions." (PMID 40559622, 2025).
lung (11 papers, 2008 to 2023). "The HOXA11 and CDKN2A genes appear to be highly promising DNA hypermethylation markers for the development of non-invasive molecular markers of lung AD." (PMID 28380439, 2017). "HOXA11 and CDKN2A EX2 could be confirmed as DNA hypermethylation markers for lung AD." (PMID 28380439, 2017). "In summary, our results showed that the promotor regions of HOXA11, CDKN2A EX2 and EYA4 were frequently methylated in human lung AD tissues." (PMID 28380439, 2017). "The tumor suppressor proteins p16 and p19ARF, corded by CDKN2A, was found to highly expressed in the CRC sections, however it seemed to be not directly related to colorectal carcinogenesis." (PMID 34699544, 2021).
head and neck tumors (9 papers, 2014 to 2023). "In summary, we propose a hitherto unknown mechanism how CDKN2A expression could be fine-tuned via the Taspase1-TFIIA signalling-pathway in head and neck tumours." (PMID 29097782, 2017). "In one report, 22% of head and neck tumors (n = 279) have a deletion in CDKN2A." (PMID 26634163, 2015).
neurodegenerative disease (8 papers, 2015 to 2022). A disorder of the central nervous system characterized by gradual and progressive loss of neural tissue and neurologic function. "All together, these findings link important stem cell regulators like Bmi1/Usp16 and Cdkn2a to Wnt signaling, and have implications for designing therapies for conditions, like DS, aging or degenerative diseases, where the Wnt pathway is hampered." (PMID 30504774, 2018).
genetic disorders (7 papers, 2014 to 2025).
hematological malignancies (7 papers, 2007 to 2024). "Epigenetic alterations to CDKN2A are being targeted by drugs such as 5-Aza-2’-dexoycytidine, approved for hematological malignancies, to induce CDKN2A promoter demethylation." (PMID 34553848, 2021). "We focused primarily on the genomic region of chromosome 9p21 since this region containing cdkn2a and cdkn2b is known to be deleted in multiple solid and hematologic malignancies." (PMID 22948084, 2012). "In normal keratinocytes, 14-3-3σ expression is accompanied by CDKN2A expression but in hematological malignancies 14-3-3σ expression was rarely accompanied by CDKN2A expression." (PMID 18036248, 2007). "CDKN2A/2B and MTAP deletion frequency were the highest among the genes analyzed and their codeletion was also previously reported in solid cancers and hematological malignancies." (PMID 36601176, 2023).
benign tumors (6 papers, 2015 to 2023). "Although p16 more typically is considered a tumor suppressor protein, high Cdkn2a/p16 levels have been detected in mouse colon tumors induced by azoxymethane, a metabolite of DMH, and in human benign tumors and high-grade malignancies." (PMID 26388957, 2015).
kidney disease (6 papers, 2013 to 2025). "Most human kidney diseases are related to accelerated cellular senescence, particularly with overexpression of CDKN2A in TECs." (PMID 39963130, 2025).
metabolic disease (4 papers, 2018 to 2023). A congenital disorder (due to inherited enzyme abnormality) or acquired (due to failure of a metabolically important organ) disorder resulting from an abnormal metabolic process. "Genome-wide association studies (GWAS) have established the cyclin-dependent kinase inhibitor (CDKN)2a locus, also called INK4a/ARF, as a hotspot influencing genetic risk for cardiovascular and metabolic diseases including T2D." (PMID 32971832, 2020).
CDKN2A also shares sentences with these, for which no sentence is quoted: squamous intraepithelial lesions (13 papers); cervical (10); Cirrhosis (10); periodontitis (10); cervical tumors (9); sarcopenia (9); brainstem glioma (8); cataract (8); psoriasis (8); undifferentiated pleomorphic sarcoma (8); age (7); Alpha-thalassemia (7); Anxiety (7); childhood cancer (7); leiomyosarcoma (7); Burkitt lymphoma (6); cardiomyopathy (6); cervical squamous cell carcinoma (6); disc degeneration (6); Malignant Rhabdoid Tumor (6); nervous system neoplasm (6); rhabdomyosarcoma (6); rheumatoid arthritis (6); adrenocortical carcinoma (5); Ataxia (5); cervical squamous intraepithelial lesion (5); COVID-19 (5); ductal carcinoma in situ (5); Glucose intolerance (5); hematological cancers (5).
A further 361 diseases each share a sentence with CDKN2A in 5 papers or fewer.